ENSG00000278144
Gene: Miscellaneous RNA gene on chromosome 11 (65,423,273 to 65,423,392, forward strand). Ensembl gene ENSG00000278144.
Gene Ontology:
Cellular component: paraspeckles
Homologues: Orthologues: mouse Gm55525 (87% identical).